CDH3 (cadherin 3)
Diseases named in the same sentence as CDH3 in open-access papers (continued):
Sharing a sentence is not in itself a finding about the gene and the disease.
tumor (continued). "Downregulation of both cadherins occurred in 19% of tumours, while only 7% of all tumours expressed CDH1 and lacked CDH3 expression." (PMID 37372088, 2023). "One portion of the SCCL/Mes‐Inf cluster was negative for KRT5/KRT14 and FOXA1/GATA3, as well as for CDH3 expression, making it distinct from basal/SCC‐like tumours." (PMID 28195647, 2017). "However, these two basal/SCC‐like tumour categories do not differ in their KRT5, KRT14/FOXA1, GATA3 ratios, their defining characteristics, or their shifts to high CDH3 and lower CDH1 expression." (PMID 28195647, 2017).
cancer (130 papers, 2005 to 2025). A tumor composed of atypical neoplastic, often pleomorphic cells that invade other tissues. "Among these, CDH1, CDH2, and CDH3 have been implicated in multiple cancers, yet their specific roles in NSCLC remain inadequately defined." (PMID 40860670, 2025). "On the other hand, possible functional modulations of cell invasiveness or adhesion have been associated with changes in CDH1 and CDH3 expression in other cancers." (PMID 38003666, 2023). "In the clinical setting, CDH3 correlates with cancer‐related signatures and associates with poor prognosis of GBM patients." (PMID 34919784, 2022). "FN1 seems to be associated with cisplatin resistance and over-expression of CDH3 correlates to a poor prognosis in carcinomas of the breast, prostate, ovary, colon and stomach." (PMID 33086649, 2020). "It has been observed that the overexpression of CDH3 (P-cadherin) is associated with the aggressiveness, invasion, and metastasis of cancer cells." (PMID 31217907, 2019). "P-cadherin is a cell-cell adhesion molecule codified by the CDH3 gene, which expression is highly associated with undifferentiated cells in normal adult epithelial tissues, as well as with poorly differentiated carcinomas." (PMID 23405208, 2013). "Similarly, cadherin 3 (CDH3) is another highly expressed gene in COAD that encodes P-cadherin and has been linked to poor prognosis in cancer patients and increased glycolysis in cancer cells." (PMID 37692839, 2023). "Cadherin‐3 (also known as P‐cadherin), a cell–cell adhesion molecule encoded by the CDH3 gene, is deregulated in several cancer types, but its relevance in GBM is unknown." (PMID 34919784, 2022). "A well-known mechanism associated with CDH3-induced cancer cell invasion is MMP activation." (PMID 36685820, 2022). "CDH3 isoform encoding for adhesion glycoprotein is a member of cadherin family responsible for cell–cell adhesion and reported for its overexpression in several cancers." (PMID 28330331, 2016). "P-cadherin, a calcium dependent cell-cell adhesion molecule encoded by the CDH3 gene, is a protein whose expression is highly associated with undifferentiated cells in normal adult epithelial tissues, as well as with poorly differentiated carcinomas." (PMID 25269858, 2014). "Cdh3 is a novel tumor-associated antigen, which can be used in cancer immunotherapy." (PMID 22291890, 2012). "This study examined the expression pattern of cadherin-3 (CDH3), a cell adhesion protein associated with cancer metastasis and poor prognosis, under oxidative stress." (PMID 40227353, 2025). "Recent studies have shown that, in the A549 cell line, ROS up-regulate cadherin-3 (CDH3), a cell adhesion protein associated with cancer metastasis and poor prognosis." (PMID 40869000, 2025). "High expression of CDH3 disrupts epithelial adhesion and fosters the development of a more mesenchymal and progenitor-like phenotype, ultimately resulting in cancer." (PMID 37151391, 2023). "Increased CDH3 expression also increases cell motility and migration in cancer by interfering with CTNND1 and CDH1." (PMID 37151391, 2023). "Downregulation of the CDH1 gene and upregulation of CDH3, CDH2, and VIM in EMT is a hallmark of cancer metastasis." (PMID 37151391, 2023). "The development of P-cadherin anticancer therapy commenced with PF-03732010, a humanized anti-CDH3 monoclonal antibody (mAb) with demonstrated antitumor activity confirmed by carcinoma mouse models." (PMID 37760501, 2023). "The results showed that the expression of ANK3 (in the proteoglycans in cancer pathway), CDH3, and CNTNAP2 (in the cell adhesion molecule pathway) was downregulated." (PMID 35745623, 2022). "ADAMTS9-AS2 recruits DNMT1/DNMT3 to the promoter region of CDH3, resulting in CpG island hypomethylation and inhibiting the expression of CDH3, thereby inhibiting cancer cell function." (PMID 35241975, 2022). "CDH3, a classical cell adhesion molecule, has been reported to be related to a variety of human cancers." (PMID 34956309, 2021).
cancer (continued). "Its role in cancer was further supported by the study showing Cadherin 3 increased the mobility of cancer cells." (PMID 34013637, 2021). "Cadherin 3 (CDH3), a classical cadherin of the cadherin superfamily, has also been linked to many types of cancer, such as colorectal, breast, and pancreatic cancers." (PMID 32873775, 2020). "Silencing of three specific CDH3 mutations on EC 3 and EC4 in canine HER2-positive cells with cancer stem cell characteristics reduced the Wnt activity and changed the morphology of the cells from rounded to spindle shaped." (PMID 31105876, 2019). "Lastly, increased expression of P-cadherin (Placental cadherin/cadherin-3/CDH3) has also been described in certain advanced carcinomas, wherein E-cadherin is again characteristically downregulated." (PMID 30895176, 2019). "This study's purpose was to determine P-cadherin expression in CRC and normal tissues and to assess plasma CDH3 levels in order to determine the relationship, if any, between cancer stage, P-cadherin expression and plasma CDH3 levels." (PMID 29142905, 2017). "In non-cancer models, CDH3 promoter was shown to be genetically regulated through direct binding of transcription factors, such as p63 and β-catenin." (PMID 23405208, 2013). "Epigenetic alternations of CDH3 with concurrent alterations in CDH3 protein expression have been correlated with adverse histopathology in a variety of cancers, such as breast, cervical, ovarian, pancreatic, gall bladder, colorectal, hepatocellular, and oral squamous cancers." (PMID 38003666, 2023). "After confirming the long‐term knockdown of CDH3/P‐cadherin, this shRNA‐based GBML18 model was validated in vitro for key cancer hallmarks, globally recapitulating the association of P‐cadherin silencing with compromised GBM cell viability and migration capacity." (PMID 34919784, 2022). "Finally, expression of CDH3, a marker of hybrid E/M state in cancer cells, was highly induced by RSV infection." (PMID 33732255, 2021). "P-cadherin (or placental cadherin) is a classical cell–cell adhesion molecule, encoded by the CDH3 gene, whose expression is highly associated with undifferentiated cells in normal adult epithelial tissues, as well as with poorly differentiated carcinomas." (PMID 31010154, 2019). "Placental cadherin (P-Cad or CDH3) has been widely studied in cancer." (PMID 26771841, 2016). "Of note, immunoreactivity analysis has provided preliminary evidence of mis-localization of CDH3 in PCa cells compared to non-tumoral counterparts, Interestingly, this alteration is also observed in other cancers and is associated to poor prognosis." (PMID 26771841, 2016). "A Spearman rank correlation analysis of the 15 cell lines with available data on DNA methylation and mRNA expression demonstrated a coefficient of correlation R = −0.58 (p = 0.023), indicating that DNA methylation-related epigenetic silencing of CDH3 expression could occur in various human cancers." (PMID 38003666, 2023). "We selected CDH3, LEF1, and MMP7 as candidate biomarkers to construct a back propagation neural network model from hub genes, which may be helpful for the early diagnosis of cancer through the high-risk early warning range." (PMID 34485109, 2021). "In particular, a paralog of CDH3 is CDH1, cadherin of the E type, a known growth and invasion suppressor whose loss of function contributes to cancer progression through augmented proliferation, invasion, and/or metastasis, and whose mutations have been correlated with various cancers." (PMID 30485296, 2018). "For instance, CDH2 and CDH3 were found activating epithelial-to-mesenchymal transition (EMT) and Cell cycle cancer-related pathways in NSCLC." (PMID 40860670, 2025). "When performing pairwise comparisons among the different stages of cancer, stage IV patients had increased expression of FGA, FGB, PERP, GPR107, CDH3 compared to controls." (PMID 39146279, 2024).
cancer (continued). "Except for CDKN1B and RELA, the expression levels of CASP7, CDH3, EIF4G1, and EIF4EBP1 were increased significantly in most individual cancer stages compared with normal samples." (PMID 35787690, 2022). "siRNAs specific for SCD and CDH3, as well as plasmids harboring full-length human SCD and CDH3 sequences, were designed and transfected into cancer cells." (PMID 32873775, 2020). "The expression levels of CDH3, IGF2BP3, HOXB7, and BIRC5 mRNA in malignant biliary strictures were significantly higher than in benign strictures (P = 0.006, <0.001, <0.001, and 0.001, respectively)." (PMID 27399126, 2016). "Using machine learning algorithms, including RF, SVM, GBM (XGBoost), and DT, the genes CDH3, DKC1, ESM1, MUSTN1, RCC2, TMT1A, and VEGFD were selected as key features from the tissue dataset to best discriminate between cancer and control samples and were used to design the predictive model." (PMID 40425785, 2025). "Prior study suggested CDH3 promoted the activation of β‐Pix/CDC42 axis through collagen fibre orientation to facilitate directional collective cell migration, which was crucial for cancer metastasis." (PMID 34013637, 2021). "Our results demonstrate that both CDH3 and PDPN are activated in advanced stage LSCC, suggesting that LSCC cancer cells may induce collective migration (CCM) to invasion and metastasis." (PMID 31217907, 2019). "Consistent with this notion, we identified a subset of this signature containing DPP4, BCAT1, CNTNAP4 and CDH3, whose expression are either the same or increased in CRPC compared to primary PC, and whose gene alterations correlate with a more rapid onset of cancer." (PMID 28055971, 2017). "In addition, OVOL1/2 is highly correlated with GRHL2 and CDH3 (positively) and with ZEB1 (negatively) in a panel of 877 cell lines from The Cancer Cell Line Encyclopedia (CCLE)." (PMID 27008704, 2016). "Therefore, the relatively high levels of CDH3, OVOL2, and GRHL2 in patients with poor survival might highlight the role of hybrid E/M phenotype in metastatic progression, at least in these carcinomas." (PMID 27008704, 2016).
benign tumours (3 papers, 2012 to 2018). "Of these, 15 proteins (PRSS8, MK, WFDC2 (HE4), IL-10, SOD2, PARP-1, hK11, PVRL4, MUC-16 (CA125), FR-alpha, CDH3, NTRK3, IL-8, IL-17C, EN-RAGE) were selected from the comparison between OC stage I–IV and benign tumors." (PMID 30519148, 2018).
retinopathies (2 papers, 2018). "This is an unusual and infrequently encountered pattern of degeneration, but one that is shared with other monogenic retinopathies, where the underlying gene regulates cell–cell adhesion (ADAM9, CDH3)." (PMID 29391521, 2018). "Out of the remaining 60 patients, 7 patients (12%) revealed one potentially disease-causing variant in a gene causing recessive retinopathy in combination with a phenotype usually associated with mutations in the respective gene (ABCA4, n = 5; CDH3, n = 1; CERKL, n = 1)." (PMID 29555955, 2018).
infection (1 paper, 2025). The state of being infected such as from the introduction of a foreign agent such as serum, vaccine, antigenic substance or organism. "In future studies, lentiviral infection will be used to establish stable CDH3 overexpression or knockdown cell lines to further investigate the long-term effects of CDH3 on cell morphology." (PMID 40227353, 2025).
CDH3 also shares sentences with these, for which no sentence is quoted: ovarian carcinoma (15 papers); hypotrichosis (7); lymph node metastasis (5); metastatic disease (5); triple-negative breast carcinoma (5); cervical squamous cell carcinoma (4); ovarian tumor (4); squamous cell carcinoma (4); cervical cancer (3); Ectrodactyly (3); endometrial cancer (3); bladder tumors (2); cervical dysplasia (2); colorectal adenocarcinoma (2); epidermal cyst (2); infiltrating ductal breast carcinomas (2); Lung Squamous Cell Carcinoma (2); mucinous carcinoma (2); retinitis pigmentosa (2); acromegaly (1); adenocarcinoma (1); adenocarcinoma of the gall bladder (1); adenosquamous carcinoma of the gallbladder (1); Alopecia universalis (1); Alzheimer disease (1); basal cell carcinoma (1); brain glioma (1); brain inflammation (1); carcinoma in situ (1); carcinosarcoma (1).
A further 52 diseases each share a sentence with CDH3 in 1 paper.